SRRT (serrate, RNA effector molecule)
Description:
Acts as a mediator between the cap-binding complex (CBC) and the primary microRNAs (miRNAs) processing machinery during cell proliferation. Contributes to the stability and delivery of capped primary miRNA transcripts to the primary miRNA processing complex containing DGCR8 and DROSHA, thereby playing a role in RNA-mediated gene silencing (RNAi) by miRNAs. Binds capped RNAs (m7GpppG-capped RNA); however interaction is probably mediated via its interaction with NCBP1/CBP80 component of the CBC complex. Involved in cell cycle progression at S phase. Does not directly confer arsenite resistance but rather modulates arsenic sensitivity. Independently of its activity on miRNAs, necessary and sufficient to promote neural stem cell self-renewal. Does so by directly binding SOX2 promoter and positively regulating its transcription (By similarity).
Synonyms: ARS2; ASR2; serrate
Tractability: Small molecule: a structure with a bound ligand is known. PROTAC: UniProt records ubiquitination sites on it; ubiquitination databases record sites on it; its protein half-life has been measured.
Gene: Protein-coding gene on chromosome 7 (100,875,065 to 100,888,664, forward strand). Ensembl gene ENSG00000087087.
Subcellular location: Nucleus, nucleoplasm; Cytoplasm
Subcellular location (Human Protein Atlas): Nucleoplasm
Pathways (Reactome):
Metabolism of RNA: Nuclear RNA decay; mRNA Polyadenylation; mRNA Splicing - Major Pathway
Disease: Dengue Virus-Host Interactions
Gene expression (Transcription): RNA polymerase II transcribes snRNA genes
Gene Ontology:
Molecular function: mRNA cap binding complex binding; protein binding; protein-macromolecule adaptor activity; RNA binding; DNA binding; nucleic acid binding
Biological process: primary miRNA processing; neuronal stem cell population maintenance; regulation of DNA-templated transcription; response to arsenic-containing substance
Cellular component: nucleoplasm; protein-containing complex; ribonucleoprotein complex; cytoplasm
Genetic constraint (gnomAD): Loss-of-function variants: 32 observed, 106.33 expected, observed/expected ratio (o/e) 0.3, 90% interval 0.23 to 0.4. The upper end of that interval is the gene's LOEUF score, 0.4, which puts it in group 1 of 6, group 1 being the genes least tolerant of losing a copy. Missense variants: 986 observed, 1,254 expected, observed/expected ratio (o/e) 0.79, 90% interval 0.75 to 0.83. Synonymous variants: 525 observed, 469.81 expected, observed/expected ratio (o/e) 1.12, 90% interval 1.04 to 1.2.
Homologues: Orthologues: macaque SRRT (99% identical), chimpanzee SRRT (99% identical), pig SRRT (99% identical), dog SRRT (99% identical), guinea pig SRRT (99% identical), rat Srrt (98% identical), mouse Srrt (97% identical), zebrafish srrt (72% identical), tropical clawed frog srrt (71% identical), Drosophila melanogaster Ars2 (45% identical), Caenorhabditis elegans srrt-1 (36% identical).
Diseases named in the same sentence as SRRT in open-access papers:
SRRT is named in the same sentence as 38 diseases in open-access papers, as found by Europe PMC text mining. Sharing a sentence is not in itself a finding about the gene and the disease. The quoted sentences say what the papers report.
glioblastoma (3 papers, 2018 to 2022). The most malignant astrocytic tumor (WHO grade IV). "Upregulated SRRT gene, also known as ARS2, is associated with increased cell proliferation and poor overall survival by modulating the miR-6734-3p/p27 axis and miR-6798-3p in myeloid leukemia and glioblastoma, respectively." (PMID 36293493, 2022).
acute myeloid leukemia (2 papers, 2019 to 2023). Acute myeloid leukemia (AML) is a group of neoplasms arising from precursor cells committed to the myeloid cell-line differentiation. "Further, in acute myeloid leukemia, SRRT is highly expressed and regulates the miR-6734-3p/p27 axis, which is known to regulate cell proliferation and colony formation in acute myeloid leukemia." (PMID 37345203, 2023).
hepatocellular carcinoma (2 papers, 2019 to 2023). A malignant tumor that arises from hepatocytes. "Moreover, studies have found that SRRT is involved in biogenesis of miR-21 in hepatocellular carcinoma, and subsequent knockdown of SRRT has resulted in the inhibition of miR-21 expression and cellular proliferation." (PMID 37345203, 2023).
bipolar disorder (1 paper, 2011). A disorder of the brain that causes unusual shifts in mood, energy, activity levels and the ability to carry out day-to-day tasks. "Several previously unidentified disease marker genes and drug targets, such as SBNO2 (schizophrenia), SEC24C (bipolar disorder), and SRRT (major depression), were identified based on statistical and topological analyses of the PPI network." (PMID 22373040, 2011). "These genes included SBNO2, CEACAM5, AKAP1, UBC, ACTB, UBB, and FOS for schizophrenia; SEC24C, PGLYRP1, ARHGAP4, RPL22, SLC6A11, and SYK for bipolar disorder; and SRRT, PARK2, LILRA4, STK17A, IGFBP2, and NF1 for major depression." (PMID 22373040, 2011). "Apart from this study, SBNO2, SEC24C and SRRT have never been associated with schizophrenia, bipolar disorder, or major depression; these genes did not form PPI with any of our abnormally expressed marker genes, either." (PMID 22373040, 2011).
major depression (1 paper, 2011). "SRRT was a gene of which the probe had the lowest P value in the t-test comparing major depression and control samples." (PMID 22373040, 2011).
prostate carcinoma (1 paper, 2023). A carcinoma that arises from epithelial cells of the prostate gland. "In the current study, we have investigated the potential role of SRRT in prostate cancer progression and its association with common genetic aberrations in the lethal disease." (PMID 37345203, 2023). "This is the first study that has investigate the potential role of the SRRT gene in prostate cancer using clinical samples." (PMID 37345203, 2023). "Gene set enrichment analysis (GSEA) of RNAseq data from the TCGA PRAD cohort indicated that SRRT may play a potential role in regulating the expression of genes involved in prostate cancer aggressiveness." (PMID 37345203, 2023). "Gene set enrichment analysis suggested that SRRT may play a role in regulating the expression of genes contributing to prostate cancer aggressiveness." (PMID 37345203, 2023). "Finally, our data suggested that SRRT high-expression may play a role in regulating the expression of genes involved in prostate cancer aggressiveness and development of resistance to chemotherapy in prostate cancer." (PMID 37345203, 2023).
cancer (10 papers, 2010 to 2024). A tumor composed of atypical neoplastic, often pleomorphic cells that invade other tissues. "Across the 18 cancers in their study, certain proteins stood out as pan-cancer markers such as THBS2, VCAN, SRRT, and TNC." (PMID 39698114, 2020).
tumor (9 papers, 2010 to 2025). "In the setting of human disease, ARS2 (SRRT) was significantly upregulated in CD8+ T cells from human tumors and tumor-draining lymph nodes." (PMID 38233562, 2024). "Additionally, proteins involved in the regulation of the cell cycle (e.g., ATM and STAT3), cell proliferation (e.g., LYN and SRRT), metabolism (e.g., GOT2, PPP1CA, and PYGB), and the regulation of Ca2+ flux (e.g., ANXA6 and CALM1) were also found phosphorylated in the tumor cells." (PMID 40129242, 2025).
SRRT also shares sentences with these, for which no sentence is quoted: infection (6 papers); cholangiocarcinoma (3); glioma (3); viral infection (3); breast carcinoma (2); hearing loss (2); leukemia (2); lymphoma (2); mitochondrial disease (2); astrocytoma (1); B‐cell lymphoma (1); Charcot-Marie-Tooth disease (1); chronic lymphocytic leukemia (1); co-infection (1); colon carcinoma (1); diffuse large B-cell lymphoma (1); experimental autoimmune encephalomyelitis (1); Leukoencephalopathy (1); mantle cell lymphoma (1); melanoma (1); myeloid leukemia (1); osteosarcoma (1); Perrault syndrome (1); pituitary tumours (1); plasma cell dyscrasia (1); pontocerebellar hypoplasia (1); primary central nervous system lymphoma (1); schizophrenia (1); Sensorineural hearing impairment (1); Skeletal myopathy (1).